LEP (leptin)
Diseases named in the same sentence as LEP in open-access papers (continued):
Sharing a sentence is not in itself a finding about the gene and the disease.
Obesity (continued). "The obesity-induced leptin resistance has been the interest of scientists for several years." (PMID 31780867, 2019). "This dysregulation of leptin sensing and signaling may contribute to and perpetuate obesity in addition to promoting IR in cats." (PMID 31533709, 2019). "Dysregulation of leptin and insulin signaling pathways within this brain region may contribute not only to the development of obesity, but also systemically affect the peripheral organs, thereby manifesting as metabolic diseases." (PMID 31660128, 2019). "In addition to MC4R, loci in the FTO gene have been consistently linked with the risk of obesity with FTO being highly expressed in the hypothalamus and playing a role in the ghrelin, leptin, and melanocortin pathways." (PMID 30764585, 2019). "Like leptin, resistin is positively correlated with obesity." (PMID 31316526, 2019). "The circulating spexin level was inversely correlated with leptin in adolescents with obesity." (PMID 31133851, 2019). "The most widely used monogenic models of obesity are defective in leptin signaling." (PMID 30823474, 2019). "Several soluble factors contribute to the obesity-associated inflammation, such as proinflammatory cytokines (IL-6, PGE2 and TNFα), chemokines (CCL2, CCL5), and dysregulation of adipokines (increased leptin and decreased adiponectin)." (PMID 31340438, 2019). "The extract might have also led to an increase in energy expenditure, inhibited the differentiation and proliferation of preadipocytes, and stimulated satiety signals (such as leptin) thereby resulting in the reduction of body and obesity index." (PMID 31565046, 2019). "While obesity and ob/ob genotype are associated with a reduction in Bacteroidetes/Firmicutes ratio in humans and male mice, respectively, the effects of leptin on gut microbiota have not been studied in females." (PMID 31882890, 2019). "The adrenergic overdrive which has been supposed to contribute to the pathogenesis of cardiovascular complications and metabolic disorders in obesity might directly connect to the increasing plasma leptin concentration." (PMID 31682617, 2019). "However, adipose tissue and muscle also act as endocrine organs that release various cytokines, such as leptin, adiponectin, tumor necrosis factor-alpha, and interleukin-6, and alter insulin sensitivity in obesity and metabolic syndrome." (PMID 31470507, 2019). "Several studies have reported that leptin provides a link between obesity and lung diseases." (PMID 30832310, 2019). "Obesity increases the circulation of inflammatory mediators and leptin resistance." (PMID 31052312, 2019). "In order to investigate whether obesity/diabetes leads to adipose tissue neuropathy, we used BTBR mice with the ob/ob leptin-deficient mutation (MUT)." (PMID 31509546, 2019). "Leptin resistance in the hypothalamus has an essential role in obesity." (PMID 31600939, 2019). "The adipokines leptin, resistin, and TNF-α are also involved in lipid and glucose metabolisms, and their enhanced expressions have been linked with the development of diabetes and obesity." (PMID 30863274, 2019). "Generally, mutations in leptin (LEP), the leptin receptor (LEPR) and the melanocortin 4 receptor (MC4R) represent the most common cause of monogenic forms of obesity and mutations within these genes have been demonstrated to cause childhood morbid obesity in probands of various ethnicities." (PMID 31488071, 2019). "Numerous studies have found a significant correlation between obesity and many autoimmune diseases, adipokines such as leptin, adiponectin and resistin may be key players in interactions among them." (PMID 31118946, 2019). "The variation in leptin concentrations observed among studies could be strongly influenced by many confounders, since obesity, periodontal and metabolic diseases have different and sometimes complimentary effects on its concentration." (PMID 30758470, 2019).
Obesity (continued). "Triglycerides, which are elevated in obesity, are known inhibitors of leptin transport, and so may contribute to a feed-forward cycle of leptin deficiency in the brain that leads to hyperphagia and further increases in triglycerides." (PMID 30986918, 2019). "The adipokines leptin, resistin, and TNF-α are also involved in glucose metabolism, but unlike adiponectin, their elevated levels are associated with the development of diabetes and obesity." (PMID 31514360, 2019). "ER/mitochondrial stress induces obesity-related high leptin levels." (PMID 31498850, 2019). "Since in adipose tissue in obesity autophagy genes’ mRNA and protein levels were increased, we also determined whether leptin could elevate the expression of such gene products in adipocytes." (PMID 30676227, 2019). "While very preliminary, our findings might suggest that the neurotrophic and neuroprotective effects of leptin are modulated in overweight and obesity." (PMID 31751856, 2019). "Furthermore, using the gene expression signature of celastrol as a query on CMap uncovered that withaferin A is also a chemical chaperone and a leptin sensitizer, and significantly ameliorates obesity." (PMID 31717493, 2019). "Relationship between leptin and obesity could be considered as a part of metabolic syndrome (MS), the pathological condition comprising of also dyslipidaemia, hyperglycaemia, and high blood pressure." (PMID 31091785, 2019). "Had leptin become a successful therapy for obesity, royalty payments would have been enormous." (PMID 30357355, 2019). "Identifying pertinent negative feedback mechanisms could help us to gain insight into how leptin resistance may occur at the β-cell level in pathological states such as obesity or type 2 diabetes." (PMID 31151172, 2019). "Hypothalamic leptin-mediated signaling may contribute to the exaggerated sympathoexcitation of obesity." (PMID 31803004, 2019). "Obesity promotes steatosis and is characterized by leptin resistance." (PMID 31222048, 2019). "The development of central resistance to the effect of insulin, leptin as well as other hormones effective on energy metabolism and chronically altered in obesity may also explain the BMI-related differences in brain glucose metabolism." (PMID 31600734, 2019). "However, research on obesity and metabolism control continues to focus on this interesting hormone because the prevention and treatment of leptin resistance represents one of the greatest challenges in the treatment of obesity." (PMID 31717265, 2019). "Additionally, obesity is involved in BC development through the release of some adipokines, identified as “released hormones” represented by adiponectin, leptin, estrogen, and insulin." (PMID 31684107, 2019). "Serum leptin level is proportional to the adipocytes; hence, we analyzed whether spilanthol improves obesity and decreases leptin levels." (PMID 31052312, 2019). "Therefore, the satietyogenic effect presented by TTIp in this study can also be justified by the improvement of the sensitivity to CCK, regardless of its plasma increase, which is conditioned by the reduction of leptin, which is usually high in obesity." (PMID 30818882, 2019). "Moreover, leptin acutely downregulates preproinsulin mRNA expression in ob/ob mice and humans with obesity as well as inhibiting pancreatic β-cell function." (PMID 31500090, 2019). "However, in obesity, leptin is often chronically elevated resulting in central resistance to the effects of the molecule." (PMID 31427957, 2019). "Additionally, our results showed that the LEP rs7799039 A was a protective factor against T2D in subjects with obesity." (PMID 30764545, 2019). "Because various neuropeptides can be delivered into the central nervous system through an intranasal administration route, intranasal leptin might prove an effective treatment approach for obesity." (PMID 31717265, 2019).
Obesity (continued). "Notably, leptin concentrations are significantly increased in obesity and T2D, and positively correlated with adipose mass, indicating the occurrence of leptin resistance." (PMID 31736870, 2019). "The Janus kinase (JAK)-signaling transducer and activator of transcription 3 (STAT3) pathway regulates key white adipocyte functions, and the severity of its deregulation in obesity correlates with important pathological outcomes, including leptin and insulin resistance." (PMID 31781039, 2019). "Here, we interrogate this interaction and demonstrate that obesity-altered ASCs promote metastasis of TNBCs through leptin signaling which has implications for discovering novel therapeutic options in a malignancy that has an urgent need for novel targeted therapies." (PMID 31118047, 2019). "Higher serum leptin and lower adiponectin levels due to obesity may contribute to the heightened pro-inflammatory cytokine production, as well as to the poor responsiveness to infection stimuli in DIO mice." (PMID 31134099, 2019). "Obesity may result in decreased intestinal leptin/ObR-b binding, distinct phylogenetic clusters of ileal bacterial communities, increased intestinal inflammatory injury and the insufficient intestinal epithelial cells proliferation during AP attack." (PMID 30635594, 2019). "However, the leptin/adiponectin ratio, which is a marker of metabolic disease and obesity, was decreased in both the CLE and LU groups." (PMID 31208033, 2019). "Using several well-established mouse obesity models such as high fat diet (HFD) induced obese mouse model and leptin deficient mouse model, it was found that obesity is associated with increased expression of phosphorylated IRE1, PERK, and JNK in adipose tissue and the liver." (PMID 32117210, 2019). "This study introduced adiponectin and leptin as indicator of MetS and obesity respectively." (PMID 31341853, 2019). "Reduced adiponectin and increased leptin level, which are frequently observed in obesity could induce AHR17,18." (PMID 31666643, 2019). "On the other hand, recent data on the paradoxical effect of obesity on cancer immunotherapy efficacy has brought some controversy, since the proinflammatory effect of leptin may help the effect of immune checkpoint inhibitors." (PMID 31380268, 2019). "Future research may eventually identify novel approaches to broaden the utility of leptin therapy in obesity." (PMID 30357355, 2019). "However, defective production of LEP is associated with obesity, and LEPR/LEPROT DNAm has been demonstrated to interact with genotype to influence both leptin levels and BMI." (PMID 31464656, 2019). "Genetic deficiency of leptin or its receptor, in both mice and humans, “fools” the brain into thinking that fat stores are absent, resulting in extreme hunger and obesity." (PMID 31245374, 2019). "Given the high prevalence of obesity, efficacy of leptin in even a small subset of obese patients could be an important therapeutic advance." (PMID 30357355, 2019). "Licochalcone A could significantly attenuate serum leptin levels and promote serum adiponectin levels to reduce obesity and regulate insulin sensitivity in HFD-induced obese mice." (PMID 31083505, 2019). "Leptin is only one, out of hundreds of peptides, which are altered in obesity." (PMID 30676227, 2019). "Leptin, as a well-known obesity marker, enhances the production of TNF and IL-6 in monocytes." (PMID 31208019, 2019). "Of the seven obesity/diabetes‐related hormones measured, leptin was the only factor that differed between Park2 KO and WT mice on both diets, where plasma levels were 65% and 94% less in RC‐ and HFD‐fed Park2 KO compared with WT mice, respectively (p < .05, p < .001)." (PMID 31724300, 2019). "Specifically, adiponectin, A:L, and A:R showed a negative associations whereas leptin, and L:R correlated positively with the obesity indices." (PMID 31416473, 2019).
Obesity (continued). "Additionally, it was reported to be positively correlated with serum leptin levels in a study of diet-modified obesity." (PMID 30813350, 2019). "This is because regulation is highly complex and it is known that other genes may also influence leptin levels, as well as on the effect of leptin on obesity and related diseases." (PMID 31766143, 2019). "By contrast, obesity alters iron homeostasis as a consequence of excess adipose tissue, which triggers a low grade chronic inflammation involving cytokines such as interleukin 6 (IL-6) and leptin." (PMID 30909605, 2019). "The serum leptin level is highest at night and lowest in the morning; as the leptin level rises, it increases the appetite via its effects on the brain, resulting in weight gain and obesity." (PMID 31687279, 2019). "In addition to inflammation, it was suggested that leptin plays an important role in the development of oxidative stress in obesity by inducing production of reactive intermediates such as H2O2 and hydroxyl radicals." (PMID 30641979, 2019). "Therefore, our results indicate that adequate sleep time in childhood appears to reverse the adverse effects of BMI-related loci on obesity from childhood to adulthood, particularly through the leptin pathway." (PMID 31285522, 2019). "Previous studies showed that resveratrol could improve obesity and insulin resistance via regulated leptin levels in serum." (PMID 31083505, 2019). "A meta-analysis of the influence of adipokine polymorphisms in adipokine genes (LEP, ADIPOQ, IL-1β, IL-6, and TNF-α) in obesity susceptibility showed that there was not association with the risk of obesity and LEP variants in adults." (PMID 31354816, 2019). "However, the relationship between obesity, leptin, and circulating Treg level, as well as the occurrence of systemic inflammation in dogs and in other domestic mammalians are still poorly understood." (PMID 31091785, 2019). "Many species-specific OCRs under positive selection, regardless of species or state-change, are closest to genes involved with biologically plausible functions for adipose tissue, including browning of fat, cell differentiation, leptin regulation, and obesity and related diseases." (PMID 31233101, 2019). "In obesity, the levels of leptin are even more elevated due to leptin resistance." (PMID 31416473, 2019). "Finally, a recent study using an animal model has indicated that leptin resistance during obesity is important to AVN pathogenesis." (PMID 30794689, 2019). "Not surprisingly, inactivating mutations in leptin or its receptor are a cause of monogenic forms of obesity." (PMID 31557979, 2019). "Additional studies are required to check the consistency of these observations which, together with our study, will contribute to a better understanding of the genetics of leptin and subsequently for obesity-cardiovascular phenotypes and interactions with diet." (PMID 31766143, 2019). "The SNP rs7799039 could impair LEP action diminishing the insulin resistance effect derived by a leptin resistant state during obesity." (PMID 30764545, 2019). "However, the anti-obesity role of leptin is usually thwarted by leptin resistance, which leads to elevated leptin levels in obesity." (PMID 31832026, 2019). "The adipokines leptin, adiponectin, resistin and omentin are thought to have important roles in human obesity and glucose homeostasis; however, their functions in the pathophysiology of feline diabetes mellitus and obesity are poorly understood." (PMID 31533709, 2019). "However, contribution of miR-143 to the formation of this metabolic disorder is still unclear, seeing that obesity comes with higher leptin secretion, and the complexity of the leptin resistance phenomenon." (PMID 31408957, 2019).
Obesity (continued). "Our data suggested that leptin may be related to the recovery of muscle and bone enhanced by obesity in mice; further studies are required to elucidate the mechanisms by which the reloading induces the recovery of muscle and bone in mice fed HFD." (PMID 31648235, 2019). "Some research has found a significant correlation between leptin messenger RNA (mRNA) expression in advanced human OA cartilage and BMI, suggesting that leptin could serve as a metabolic link between obesity and OA." (PMID 30917508, 2019). "As expected, leptin treatment reverted the obesity phenotype." (PMID 30818874, 2019). "Other obesity-related metabolic factors that might have direct or indirect effects on brain function are adipose-tissue derived signaling hormones like leptin and adiponectin." (PMID 31427957, 2019). "Collectively, these events promote leptin resistance in obesity." (PMID 30915034, 2019). "The most widely researched and most significant obesity-related adipokine is leptin (LEP)." (PMID 31592340, 2019). "Obesity goes along with elevated leptin levels and leptin resistance, which may lead to central deficiency and impaired beneficial action of this hormone in the brain." (PMID 31427957, 2019). "Additionally, LPS has been repeatedly shown to positively related to obesity and especially adipocytokines, such as SC-LCBs-increased adiponectin, and decreased leptin, resistin, and TNF-α." (PMID 31374958, 2019). "Although recombinant leptin therapy has not effectively resulted in weight loss for patients with exogenous obesity, it has been effective in patients with congenital leptin deficiency." (PMID 32010059, 2019). "This study enriched a series of pathways related to energy metabolism, including TCA cycle II (eukaryotic), acetone degradation I, fatty acid beta-oxidation I, fatty acid beta-oxidation III, ketogenesis pathway, leptin signaling in obesity, and superpathway of cholesterol biosynthesis." (PMID 31258820, 2019). "Especially, DK known to cross BBB could be a therapeutic agent for obesity by decreasing leptin resistance." (PMID 31600939, 2019). "This was associated with other anti-obesity effects such as reduced serum total cholesterol, HDL-C, LDL-C, triglycerides, glucose, leptin, AST/ALT, lipase, and reduction in harmful enzymatic activities done by β-glucosidase, β -glucuronidase, and tryptophanase." (PMID 30678355, 2019). "Interestingly, leptin, an obesity hormone, was upregulated in oncogenic hepatocytes and overfeeding groups." (PMID 30718259, 2019). "The levels of circulating leptin have been found to be elevated in the obese condition and therefore may be related to the onset and maintenance of a hyper-sympathetic state during obesity." (PMID 31803004, 2019). "As such, using low LEP levels as biomarkers, LEP analogs or other receptor agonists could be developed as obesity therapy in a subgroup of obese individuals." (PMID 31878053, 2019). "For example, obese individuals with high circulating levels of leptin, the adipokine secreted in large amounts during obesity, may have enhanced local immune responses against respiratory pathogens and increased host defense mechanisms in the lung." (PMID 30814978, 2019). "Additionally, as recently demonstrated, leptin stimulated lipolysis is mediated at least in part by sympathetic activation of scWAT, further underscoring how adipose neuropathy can contribute to metabolic dysfunction through obesity-induced leptin resistance." (PMID 31509546, 2019). "Interestingly, leptin signaling has also been suggested to be one of the circulating factors connecting obesity and the consequent reproductive dysfunction, being the reproduction defects reverted by pharmacological administration of leptin." (PMID 31178685, 2019). "Leptin levels are paradoxically increased in situations of obesity." (PMID 29340500, 2019). "However, levels of circulating leptin increase with obesity, whereas ghrelin levels decrease with obesity and aging." (PMID 30986918, 2019).